RNU6-376P (RNA, U6 small nuclear 376, pseudogene)
Gene: Small nuclear RNA gene on chromosome 11 (118,702,342 to 118,702,447, forward strand). Ensembl gene ENSG00000207462.
Homologues: Orthologues: chimpanzee U6 (99% identical), dog U6 (81% identical), mouse Gm24002 (79% identical), pig U6 (79% identical). Paralogues in human: RNU6-38P (88% identical), RNU6-86P (88% identical), RNU6-28P (87% identical), RNU6-422P (87% identical), RNU6-43P (87% identical), RNU6-774P (87% identical), RNU6-333P (86% identical), RNU6-822P (86% identical), RNU6-891P (86% identical), RNU6-1011P (85% identical), RNU6-11P (85% identical), RNU6-1216P (85% identical), and 1286 more.